FOXM1 (forkhead box M1)
Diseases named in the same sentence as FOXM1 in open-access papers (continued):
Sharing a sentence is not in itself a finding about the gene and the disease.
Obesity (19 papers, 2013 to 2025). Accumulation of substantial excess body fat. "FoxM1 deficiency in β-cells also produced a striking phenotype in terms of obesity-related β-cell increases." (PMID 29208957, 2017). "In pancreatic islet β-cells, FOXM1 is closely associated with obesity." (PMID 37238726, 2023). "Collectively, these results indicate that β-cell proliferation via neuronal signals is mediated by activation of the FoxM1 pathway in β-cells, which may underlie the maintenance of glucose homeostasis during obesity development." (PMID 29208957, 2017). "FoxM1 is a critical transcription factor in cell cycle progression and plays important roles in adaptive β cell proliferation during obesity mediated by the interorgan system linking the liver to the pancreas." (PMID 40337860, 2025). "The blockage of this transmission, including vagotomy, can inhibit the activation of the FOXM1 pathway in β-cells induced by obesity and inhibit β-cell expansion, a molecular mechanism of compensatory β-cell proliferation." (PMID 37238726, 2023). "FOXM1 is upregulated in obesity and helps in β-cell proliferation as a compensatory mechanism in IR." (PMID 36232337, 2022). "FOXM1 and CXCR4, as the most important key genes, were overexpressed in obesity and BC, and its overexpression was associated with high occurrence and worse outcome of BC." (PMID 35481418, 2022). "Neuronal signals regulate obesity-induced β-cell proliferation by a forkhead box M1 (FoxM1) dependent mechanism." (PMID 33494388, 2021). "As observed in L-MEK-mice, the vagotomy procedure completely blocked obesity-induced upregulations of Foxm1, its target genes, and that of Mki67." (PMID 29208957, 2017). "Blockade of this relay, including vagotomy, inhibits obesity-induced activation of the β-cell FoxM1 pathway and suppresses β-cell expansion." (PMID 29208957, 2017). "First, we observed that FoxM1 was upregulated in islets of obesity model mice." (PMID 29208957, 2017). "In particular, whether FoxM1 upregulation is involved in obesity-induced β-cell proliferation and, if so, how β-cell FoxM1 is activated, have yet to be determined." (PMID 29208957, 2017). "FOXM1 is involved in cell proliferation, is necessary for the maintenance of adult beta-cell mass, beta-cell proliferation and glucose homeostasis, and was shown to be up-regulated in obesity." (PMID 28644415, 2017). "Thus the vagal factors-β-cell FoxM1 pathway plays prerequisite roles in promoting β-cell proliferation and maintaining glucose homeostasis during obesity development." (PMID 29208957, 2017). "Thus activation of the hepatic ERK pathway during obesity development is involved in activation of the FoxM1 pathway in β-cells, thereby increasing β-cell mass." (PMID 29208957, 2017). "Likewise, β-cell FoxM1 production is upregulated in response to obesity." (PMID 38229396, 2023). "The vagotomy procedure blocked β-cell FoxM1 activation and β-cell increases in both L-MEK-mice and obesity model mice." (PMID 29208957, 2017). "Therefore, the FOXM1/PLK1/CENP-A signaling pathway is vital in β-cell senescence, diet-induced obesity (DIO), pregnancy, and acute insulin resistance." (PMID 37238726, 2023). "We provide evidence that Tcf19 expression is positively correlated with islet expansion in nondiabetic obesity and that Tcf19 expression increases in response to FoxM1 overexpression, a known driver of β-cell proliferation." (PMID 23860123, 2013). "Notably, hepatic ERK activation and marked increases in the expression levels of FoxM1 and its target genes as well as that of the Mki67 gene were observed as early as only 1 week after HFD loading when obesity had not yet become evident." (PMID 29208957, 2017).
acute myeloid leukemia (18 papers, 2012 to 2025). Acute myeloid leukemia (AML) is a group of neoplasms arising from precursor cells committed to the myeloid cell-line differentiation. "Forkhead box M1 (FOXM1), a Forkhead family transcription factor, is often overexpressed in a variety of human cancers, including acute myeloid leukemia (AML), and is strongly associated with therapy resistance and unfavorable outcomes." (PMID 39880086, 2025). "further elucidated the inhibitory potential of miR-370 on acute myeloid leukemia progression via FOXM1 targeting." (PMID 37817774, 2023). "Lastly, in two studies of acute myeloid leukemia, the silencing and reduction of FOXM1 led to decreased tumorigenic properties in both in vitro and in vivo models." (PMID 31390744, 2019). "For example, restoration of miR-370 expression led to downregulation of FOXM1 in acute myeloid leukemia, promoting cell growth arrest and senescence." (PMID 28030816, 2017). "FOXM1 and its targets such as Cyclin B1 have been implicated in promoting proliferation through modulating cell cycle progression in acute myeloid leukemia (AML)." (PMID 25365263, 2014). "In acute myeloid leukemia cell lines, FoxM1 is involved in G2/M and S phase checkpoints and enhances proliferation." (PMID 23110199, 2012). "Nuclear FOXM1 confers resistance to standard acute myeloid leukemia chemotherapy and may represent a potential therapeutic target." (PMID 30089730, 2018). "Curcumin was reported to suppress FoxM1 expression in human acute myeloid leukemia (AML)." (PMID 26046466, 2015). "Given that, in acute myeloid leukemia, NPM1 physically binds to FOXM1 via the portion of NPM1 that is not retained in the NPM-ALK fusion." (PMID 31390744, 2019).
head and neck squamous cell carcinoma (16 papers, 2009 to 2025). A squamous cell carcinoma that arises from any of the following anatomic sites: lip and oral cavity, nasal cavity, paranasal sinuses, pharynx, larynx, and salivary glands. "Previous literature has implicated the sustained expression of FOXM1 in numerous human cancers, including head and neck squamous cell carcinoma (HNSCC)." (PMID 34447693, 2021). "C6orf136 is a conserved gene, which is hypermethylated responding to oncogene FOXM1 expression in head neck squamous cell carcinoma tissue cells." (PMID 36894917, 2023). "Qiu and colleagues reported that the blockade of MnSOD/FoxM1 signaling in head and neck squamous cell carcinoma cells results in the inhibition of expression of EMT-related transcription factors and MMP-2." (PMID 35883447, 2022). "Qiu and colleagues have demonstrated that the blockade of MnSOD/FoxM1 signaling in head and neck squamous cell carcinoma cells results in the inhibition of expression of EMT-related transcription factors." (PMID 35883447, 2022). "FOXM1 overexpression is linked to the majority of human cancers but its mechanism remains unclear in head and neck squamous cell carcinoma (HNSCC)." (PMID 19287496, 2009). "We analyzed the expression of FOXM1 and hnRNP C in TCGA head and neck squamous cell carcinoma (HNSC) and found that FOXM1 was significantly up-regulated in tumor tissues compared with normal controls." (PMID 37759731, 2023). "XRCC1 and CEP55 are supposed to be direct transcriptional targets of FOXM1 in serous EOC and head-and-neck squamous cell carcinoma, respectively." (PMID 28482906, 2017). "In head and neck squamous cell carcinoma, human RNA helicase DDX3 could modulate cisplatin resistance via ALKBH5-mediated m6A demethylation of FOXM1 and NANOG." (PMID 35279083, 2022). "In this study, using primary normal human oral keratinocytes and head and neck squamous cell carcinoma (HNSCC) tumour cell lines and tumour biopsy tissues, we investigated the role of FOXM1 in the regulation of gene promoter methylation at both single gene and genome-wide levels." (PMID 22461910, 2012).
lung squamous cell carcinoma (16 papers, 2019 to 2025). "For example, elevated expression of circTP63 in lung squamous cell carcinoma was shown to be associated with accelerated tumor progression by sponging miR-873-3p and thus increased levels of FOXM1." (PMID 31575051, 2019). "In lung squamous cell carcinoma, circTP63 binds competitively to miR-873-3p and prevents it from suppressing FOXM1, thereby upregulating CENPA and CENPB and promoting cell cycle progression." (PMID 38191906, 2024). "CircTP63 acted as a miR-873-3p sponge to increase FOXM1 expression, which in turn promoted lung squamous cell carcinoma progression." (PMID 38890620, 2024). "CircTP63 functions as a ceRNA to promote lung squamous cell carcinoma progression by upregulating FOXM1." (PMID 37280654, 2023). "For example, circTP63 has conserved binding sites for miR-873-3p and promotes lung squamous cell carcinoma progression by upregulating FOXM1." (PMID 35780119, 2022). "For example, circTP63 function as a competitive endogenous RNA (ceRNA) of miR-873-3p, thereby inhibiting miR-873-3p function on FOXM1, which finally leads to upregulating FOXM1 expression and cell cycle progression in lung squamous cell carcinoma." (PMID 34660788, 2021). "Here, the authors show that the circular RNA circTP63 promotes lung squamous cell carcinoma by competing with endogenous RNA to upregulate FOXM1." (PMID 31324812, 2019). "In lung squamous cell carcinoma, circTP63 competitively binds to miR-873-3p to upregulate FOXM1, promoting the proliferation of lung squamous cell carcinoma; circSCAP interacts with the SF3A3 protein to inhibit the malignant progression of non-small cell lung cancer." (PMID 40653497, 2025). "CircTP63 is significantly upregulated in lung squamous cell carcinoma tissues and could competitively bind to miR-873-3p, which promotes lung squamous cell carcinoma progression by regulating FOXM1 expression." (PMID 34489401, 2021). "CircTP63 promotes squamous cell lung carcinoma progression by regulating FOXM1." (PMID 33618745, 2021). "In addition, FOXM1 can be upregulated by circRNA circTP63, which promotes cell cycle transition from G1/S phase to G2/M phase, thereby accelerating the proliferation of lung squamous cell carcinoma." (PMID 37240870, 2023). "CircTP63, highly expressed in lung squamous cell carcinoma (LUSC) tissues and facilitated cell cycle progression by acting as an miR-873-3p sponge to upregulate the expression of FOXM1, CENPA and CENPB." (PMID 39519039, 2024).
clear cell renal cell carcinoma (15 papers, 2012 to 2025). "Furthermore, the miR-577/CHEK2/FOXM1 axis has been linked to radiation resistance in clear cell renal cell carcinoma." (PMID 41413918, 2025). "The research paper focused on an EMT-related gene FOXM1, which is a potential predictive cancer biomarker in clear-cell renal carcinoma (ccRCC)." (PMID 39201656, 2024). "LINC01094 facilitates clear cell renal cell carcinoma radioresistance by targeting the miR-577/CHEK2/FOXM1 axis." (PMID 35047414, 2021). "The present study was conducted to investigate the expression of FoxM1 and its prognostic significance in clear cell renal cell carcinoma (ccRCC)." (PMID 23006512, 2012). "Targeting the miR-577/CHEK2/FOXM1 axis, LINC01094 promotes radioresistance in clear cell renal cell carcinoma (ccRCC)." (PMID 36568382, 2022).
esophageal cancer (15 papers, 2016 to 2025). A primary or metastatic malignant neoplasm involving the esophagus. "Recently, over-expression of FOXM1 has been associated with malignant progression of esophageal cancer." (PMID 38697979, 2024). "Taken together, this data shows a very high probability of FOXM1 being the main mediator of STL001 effects on gene expression program in esophageal cancer cells." (PMID 38697979, 2024). "One of the direct targets of miR-204 is FOXM1, and miR-204’s functional impact on esophageal cancer cell lines depends on FOXM1." (PMID 37626655, 2023). "In esophageal cancer, elevated FoxM1 expression is correlated with the malignant progression of ESCC cells and poor outcome in patients who undergo curative resection 18,19." (PMID 36860922, 2023). "In this study, we demonstrate that UA inhibits esophageal cancer cell growth, cell proliferation, and metastasis; induces apoptosis via the Akt/FOXM1 pathway; and potentiates the anti-tumor efficacy of PTX both in vivo and in vitro." (PMID 34768915, 2021). "The FOXM1C was predominantly overexpressed in esophageal cancer compared to the other FOXM1 isoforms and promoted its metastasis." (PMID 34966670, 2021). "In summary, we have demonstrated how a new UA and PTX combination treatment suppresses esophageal cancer cell growth and tumorigenesis by inhibiting FOXM1 expression via the Akt signaling pathway." (PMID 34768915, 2021). "FOXM1 is also one of the direct targets of miR-204, and the functional effect of miR-204 on esophageal cancer cells lines is also dependent on FOXM1." (PMID 30360388, 2018). "For example, miR-204 inhibits invasion and EMT phenotype of esophageal cancer cells through targeting forkhead box protein M1 (FOXM1) gene, a transcription factor which plays an important role in the activation of EMT." (PMID 27438705, 2016). "Further, we assess whether this compound sensitizes esophageal cancer cells to different chemotherapeutic drugs via mechanisms besides FOXM1 suppression." (PMID 38697979, 2024). "FOXM1 expression has evident correlations with esophageal cancer pathology." (PMID 34768915, 2021). "Therefore, targeting Akt/FOXM1 is a potential way to cure esophageal cancer, we further examined whether UA and PTX regulate the Akt/FOXM1 signaling pathway in ESCC cells." (PMID 34768915, 2021). "In line with our previous results, esophageal cancer cells treated with paclitaxel (Taxol) at sublethal concentrations showed significantly higher levels of cellular FOXM1 protein without showing prominent cytotoxic effects." (PMID 38697979, 2024). "However, other study showed there is no significantly correlation between FOXM1 expression in tumor tissue and outcome of patients with esophageal cancer." (PMID 28427178, 2017).
pancreatic ductal adenocarcinoma (15 papers, 2015 to 2024). An infiltrating adenocarcinoma that arises from the epithelial cells of the pancreas. "Transcriptional factor Forkhead box M1 (FOXM1) plays an important role in pancreatic ductal adenocarcinoma (PDAC) development and progression." (PMID 39022126, 2024). "FOXM1 binds to the Met gene promoter and enhances HGF/Met signaling in pancreatic ductal adenocarcinoma cells by transcriptionally increasing Met expression." (PMID 36591565, 2022). "VDR negatively regulates Forkhead box M1 (FOXM1) signaling and further suppresses the development of pancreatic ductal adenocarcinoma." (PMID 33614641, 2021). "RNA sequence analysis revealed that expression of the transcription factor forkhead box M1 (FOXM1) and its target genes concordantly fluctuated with expression of DKK1 in pancreatic ductal adenocarcinoma (PDAC) cells." (PMID 34117362, 2021). "Presence of this positive FOXM1 and MET feedback loop accelerate pancreatic ductal adenocarcinoma (PDA) development." (PMID 33680951, 2020). "Similarly, in pancreatic ductal adenocarcinoma cells, USP22 promotes the G1/S transition and proliferation by upregulating the expression of FoxM1, a key regulator of the G1/S and G2/M cell cycle transitions." (PMID 32063746, 2020).
pulmonary hypertension (15 papers, 2014 to 2025). Increased pressure within the pulmonary circulation due to lung or heart disorder. "Several previous studies have verified that abnormal expression of FOXM1 correlates with lung diseases such as acute lung injury, asthma, pulmonary arterial hypertension." (PMID 39711843, 2024). "Inhibition of FOXM1 expression by miR-204 or thiostrepton leads to reduced vascular remodeling in pulmonary arterial hypertension." (PMID 37108624, 2023). "Hypoxia upregulates FOXM1 expression in SMCs by increasing the release of growth factors and inflammatory cytokines from endothelial cells, contributing to pulmonary artery hypertension." (PMID 34434114, 2021). "Analogously, deletion of FOXM1 in postnatal cardiomyocytes results in cardiac fibrosis, and pulmonary artery smooth muscle cells-specific FOXM1 regulates hypoxia-induced pulmonary hypertension." (PMID 30999932, 2019). "Furthermore, several studies have displayed that FOXM1 regulates the expression of genes involved in the vascular endothelial growth factor signaling pathway and promotes angiogenesis in various cancers as well as pulmonary arterial hypertension." (PMID 33968339, 2021). "In sum, our present results illustrate that the increased expression of FOXM1 and PLK1 in PAH leads directly to increased expression of CDC2 resulting in potentiated growth hyperactivity of PASMC from patients with pulmonary hypertension." (PMID 34203295, 2021). "Other studies have confirmed that FOXM1 is upregulated in pulmonary arteries from PAH patients and animals with experimental pulmonary hypertension." (PMID 31437238, 2019). "Additionally, a recent study has shown that YAP induces the activation of forkhead box M1 (FOXM1), a transcription factor that contributes to PASMC proliferation and pulmonary hypertension." (PMID 34434114, 2021). "FOXM1 is involved in several pathophysiological conditions such as chronic obstructive pulmonary disease (COPD), asthma, acute lung injury (ALI), pulmonary fibrosis, pulmonary arterial hypertension (PAH) and cancer." (PMID 33680951, 2020). "In addition, little is known of FOXM1 and PLK1 interactions and their participation in driving vascular cell growth in pulmonary hypertension." (PMID 31437238, 2019). "Various factors originating from dysfunctional endothelial cells induce FOXM1 expression in smooth muscle cells (SMCs) and trigger FOXM1-dependent SMC proliferation, which contributes to atherosclerosis, aortic aneurysm, pulmonary vascular remodeling and pulmonary hypertension." (PMID 40561071, 2025).
basal cell carcinoma (14 papers, 2008 to 2024). A carcinoma involving the basal cells. "In basal cell carcinoma, FOXM1 expression has been shown to be dependent on GLI1, the transcriptional effector of the Hedgehog-GLI pathway." (PMID 23365673, 2013). "FOXM1 was a downstream target of an oncogenic Sonic Hedgehog signaling pathway via a glioma family zinc finger transcription factor 1 (Gli1) in basal cell carcinomas." (PMID 23087907, 2012). "We previously showed that FOXM1 was upregulated in basal cell carcinoma and recently reported that upregulation of FOXM1 precedes malignancy in a number of solid human cancer types including oral, oesophagus, lung, breast, kidney, bladder and uterus." (PMID 20187950, 2010). "However, it was not clear whether FOXM1 had a causative role in human cancer in vivo until the first evidence demonstrated that FOXM1 was upregulated in basal cell carcinomas, one of the most common human skin cancers worldwide." (PMID 23087907, 2012). "Because FOXM1 overexpression in human keratinocytes has been suggested to contribute to cell transformation leading to the development of basal cell cancer, it seems likely that FOXM1 overexpression may contribute to HPV-induced keratinocyte transformation and the development of skin cancer." (PMID 19036130, 2008). "Since GLI1 has been shown to drive expression of FOXM1 in basal cell carcinoma, there is an appealing logic to the hypothesis that EWS/FLI1 indirectly targets FOXM1 through deregulation of GLI1." (PMID 23365673, 2013). "We originally established a link between FOXM1 and tumourigenesis when we demonstrated that FOXM1 was a downstream target of Gli1 in basal cell carcinoma (BCC) and showed that of the three known alternatively spliced isoforms (FOXM1A, B and C), FOXM1B isoform was overexpressed in BCCs." (PMID 19287496, 2009). "Reports have shown that FOXM1 is transcriptionally regulated by Gli1 in basal cell carcinomas; however, whether FOXM1 is regulated at the protein level has not been reported." (PMID 23229761, 2013).